IL10 (interleukin 10)
Diseases named in the same sentence as IL10 in open-access papers (continued):
Sharing a sentence is not in itself a finding about the gene and the disease.
tumor (continued). "Lastly, immunosuppressive immature myeloid cells (MDSCs) are activated through tumor-derived exosomes (EVs) to create an anti-inflammatory and immunosuppressive microenvironment with TGF-β, IL-10, and ROS production." (PMID 38400148, 2024). "Other than immune-modulating cytokines such as IL-10, IL-17, IL-23, and TGF-β (assisting tumor growth), IFN-γ, TNF-α, GM-CSF, IL-2, IL-6, IL-17, and IL-1 stimulate immune surveillance and prevent tum development." (PMID 38951583, 2024). "Glioblastomas exhibit a TME with significant infiltration of microglia and macrophages, which can support tumor growth and invasion through the secretion of immunosuppressive cytokines like transforming growth factor beta (TGF-β) and IL-10." (PMID 39449800, 2024). "The immunosuppressive effects mediated by the M2b and M2c macrophages, along with the production of IL-10 and TGF-β, contribute to tumor progression and immune evasion." (PMID 39456702, 2024). "Recombinant mouse IL-10 has been shown to induce IFN-γ and CD8+ T cell–dependent anti-tumor immunity in vivo." (PMID 38807592, 2024). "This elevated IL-10 concentration exerts suppressive effects, resulting in reduced infiltration of CD8+ T cells and a weakened anti-tumor response in liver metastatic tissues." (PMID 38755133, 2024). "Significant correlations between ITGB1 and LGALS3 mRNA levels, and between ITGB1 and IL-10 mRNA levels, are observed in the LIHC normal and tumor tissues, and in normal liver tissues." (PMID 38793619, 2024). "IL-10 recruits M2 macrophages that contribute to TME immunosuppression and B7-H1 enhances tumor stem cell migration." (PMID 38473776, 2024). "TAM secretes pro-angiogenic and tumor-inducing chemokines such as TGF-β, IL‐10, CCL18, matrix metalloproteases, epidermal growth factors and TGF- β." (PMID 38720340, 2024). "Immunosuppressive tumor microenvironment is created by the secretion of immunosuppressive substances by tumor cells, such as TGF‐β, IL‐10, indoleamine 2,3‐dioxygenase (IDO), PGE2, or adenosine." (PMID 38882209, 2024). "Immunosuppressive GAM releases different cytokines and growth factors, such as IL-6, IL-11, IL-1β, IL-10, and TGF-β1, to promote GBM progression by activating pre-tumor signaling in GBM cells." (PMID 39156969, 2024). "It has been suggested that this monoclonal antibody can inhibit the IL10-mediated loops and downregulate BCL-2 expression, leading to tumor drug resistance reversal." (PMID 38835350, 2024). "A recent study has shown that a high concentration of extracellular K+ ions promotes the polarization of bone marrow-derived macrophages (BMDMs) toward pro-tumor M2-like TAMs with elevated expressions of Arg I, VEGF, IL-10, and OXPHOS." (PMID 39451254, 2024). "Flow cytometric analyses demonstrate significantly increased numbers of tumor-killing CD3+ CD8+ CTL in the spleen and in the contralateral distant tumor, as well as systemically increased cytokine levels of TNF-α, INFγ and IL-10 in the serum measured by ELISA." (PMID 39599834, 2024). "Antagonizing IL-10 can increase the number of CD8+ T-cells and macrophages in TIME, which has an independent destroying effect on tumor cells and increases chimeric antigen receptor (CAR) T-cell therapy efficiency." (PMID 38649887, 2024). "Explorations of IL-10 level change in MA after chemotherapy, using ID8 tumor-bearing mice, indicating a decreasing trend, though statistical significance was not achieved." (PMID 38279997, 2024). "Thus, increased IL-10 expression associated with cutAEs may be tumor-promoting and not beneficial for the patient." (PMID 38539560, 2024). "In contrast, N2-type neutrophils express higher levels of immunosuppressive molecules such as Arg-1, IL-10, and TGF-β, thus inhibiting anti-tumor immunity." (PMID 39648199, 2024). "The tumor process is accompanied by an increase in the cytokines MCP-1 and IL-10, although their role in the literature is designated as ambivalent in this process." (PMID 38891915, 2024).
tumor (continued). "Markers of tumor burden and inflammation (LDH, CRP, IL-6, IL-10, TNF-α, ferritin, fibrinogen, D-dimer) were correlated with aph-PET and car-PET features." (PMID 38649972, 2024). "Meanwhile, IL‐10, known to promote exhaustion of CD8+ tumor‐infiltrating lymphocytes and suppress the activation of natural killer cells, was the lowest in the T‐MBs + HIFU group." (PMID 39431644, 2024). "Diosmin treatment was also found to decrease the levels of immunosuppressive cytokines, such as interleukin‐10 (IL‐10) and transforming growth factor‐beta (TGF‐β), in the tumor microenvironment." (PMID 39554345, 2024). "Mechanistically, circLOC729852 facilitates the recruitment and M2 polarization of TAMs by upregulating IL‐10 via activation of the JAK2/STAT3 pathway, and the M2 TAMs promote BLCA progression by inducing IL‐10 expression in the tumour cells." (PMID 38506082, 2024). "In contrast, TAMs are polarized to the M2-like phenotype by cytokines (such as IL-10, M-CSF, or TGF-β) that are secreted by tumour cells." (PMID 38475858, 2024). "Anti-inflammatory cytokines, including IL-10, TGF-β, IL-1Ra, and IDO, facilitate the evasion of immune attacks by the tumor." (PMID 38464838, 2024). "This dual modulatory effect was mirrored in tumor-infiltrating NKT cells, where a decrease in the percentage of PD-1+, FoxP3+, IL-10+, and KLRG1 MFI+ expression was accompanied by an upregulated expression of the activating receptors NKp46 and FasL." (PMID 38892058, 2024). "Immunosuppressive substances in the tumor microenvironment, such as TGF-β and interleukin-10 (IL-10), can also limit NK cell activity." (PMID 38523646, 2024). "Cholesterol efflux transporter proteins ABCA1 and ABCG1 in macrophages 33, and the cytokines secreted by tumor cells including CTSK34, IL-10 and CSF135, have been shown to trigger the polarization of TAMs towards the M2 phenotype." (PMID 38993570, 2024). "M2-type TAMs produce anti-inflammatory mediators such as IL-10 and TGF-β, participate in type II immune responses, and promote tumor angiogenesis, proliferation, invasion, and metastasis." (PMID 38903506, 2024). "As compared with the control groups, we observed an increase in the lifespan of animals and a decrease in the tumor size, as well as a decrease in the level of TGFB1 IL-10 factors in the blood plasma." (PMID 39767665, 2024). "Conversely, M2 macrophages produce anti-inflammatory cytokines (e.g., IL-10 and TGF-β) and promote tumor growth and metastasis." (PMID 39684424, 2024). "DCs, crucial for the initiation and maintenance of immune responses, are influenced by various factors secreted by tumor cells, including VEGF, IL-6, and IL-10." (PMID 39227970, 2024). "Another study by B. bifidum and Lactobacillus acidophilus demonstrated tumor reduction through the modulation of IFN-γ and IL-10, as well as the activation of CD4 + and CD8 + cells." (PMID 38585690, 2024). "They secrete various tumor-promoting factors, such as vascular endothelial growth factor (VEGF), IL-10, and TGF-β, which foster angiogenesis, immune evasion, and consequently, tumor invasion and metastasis." (PMID 38305920, 2024). "For example, increased ad libitum FASN contributes to the functional maturation of both Treg and TAM-M2 cells; conversely, inhibition of FASN impairs the tumor-promoting effects of TAMs by suppressing TNF-α, IL-6, IL-10, and ROS expression." (PMID 39227970, 2024). "TAM secretes vascular endothelial growth factor (VEGF), TGF-β, and IL-10, and low levels of TNF-α, IL-12, and IL-1β to induce tumor blood vessel growth and angiogenesis." (PMID 39000385, 2024). "For instance, during skin injury, CD44-expressing mast cells elevate interleukin-10 expression (IL-10), which, in turn, activates fibroblasts to produce excessive HMWHA and diminish collagen deposition and inflammatory macrophage polarization." (PMID 39194478, 2024).
tumor (continued). "MDSCs that converge at or toward the tumor site can act directly on tumor cells to induce EMT and promote BC metastasis by upregulating TGF31, VEGF, and IL-10 levels." (PMID 38404689, 2024). "Other novel drugs, including pegylated interleukin 10, colony-stimulating factor 1 receptor inhibitors, CD40 agonists, and C-X-C receptor 4 inhibitors affect the tumor microenvironment and cancer cell metabolism." (PMID 39058879, 2024). "Potent immunosuppressive cytokines such as interleukin-10 (IL-10) and transforming growth factor-beta (TGF-beta) induce the Th2 phenotype, with the establishment of an immunotolerant pattern within the tumor." (PMID 38954689, 2024). "M2 macrophages, characterized by anti-inflammatory and pro-tumorigenic activity, secrete cytokines like IL-10 and TGF-β, contributing to a favorable tumor growth and progression environment." (PMID 38338162, 2024). "α-Tocopheryl succinate nanoparticles (TS-NP) prevented peritoneal dissemination, reducing tumor nodules, tumor weights, and ascites volume via VEGF-A and IL-10 levels decreasing and M2-like TAMs polarization decreasing." (PMID 38279997, 2024). "Tregs secrete inhibitory cytokines like IL-10, TGF-β, and IL-35 to suppress the cytotoxicity of tumor-specific CD8 T cells, hamper antigen presentation by DCs, and hinder CD4 helper T-cell function." (PMID 38785789, 2024). "In the 3-methylcholanthrene induced tumor mouse model, a gold‐manganese oxide nanocomposite induced hypoxia in the tumor microenvironment, and the level of pro-inflammatory cytokines: TNF-α, IL-10, and HIF-1α were decreased." (PMID 38082190, 2024). "Conversely, IL-10 and IL-12 have been verified to reduce the phosphorylation of the STAT5 gene in NK cells, contributing to tumor progression by increasing the production of VEGF-A protein and subsequent vascular endothelial growth." (PMID 39497925, 2024). "M2 macrophages secrete inhibitory cytokines such as IL-10 and TGF-β to downregulate immune responses, which has been proven to promote tumor growth and metastasis." (PMID 39494330, 2024). "Regulatory T cells (Tregs) are a subset of CD4+ T cells that maintain immune homeostasis and impede tumor immune surveillance by producing the chemokines TGF-β, IL-35 and IL-10." (PMID 38792234, 2024). "IL-10 and IL-35 released by Bregs decrease the level of IFN-γ and increase the number of Tregs and tumor cells." (PMID 38590651, 2024). "Treatment with 5-FU and probiotics reduced the protein levels of anti-inflammatory IL-10 and noticeably increased the protein levels of proinflammatory IL-6 and TNF-α in tumor tissues." (PMID 39062024, 2024). "When using UALCAN to examine CK expression in HNSCC from the TCGA database, it is evident that IL-1β, IL-10, and TNF are highly expressed in tumor tissues with statistical significance (P < 0.01)." (PMID 38920620, 2024). "Amongst the up-regulated genes, we identified factors known to foster anti-tumor immunity such as CXCL11 (log2 = 2.2), IL-10 (log2 = 2.3), and ICAM-1 (log2 = 1.3)." (PMID 38228372, 2024). "This polarization is driven by CSF-1R signaling, which enhances the secretion of immunosuppressive cytokines such as IL-10 and TGF-β, supporting tumor growth by inhibiting cytotoxic T cell activity and promoting regulatory T cell expansion." (PMID 39796695, 2024). "Immune modulators secreted by tumor cells, including TGF-β, IL-10, and CRP, impair lymphocyte action in systemic inflammation." (PMID 39459558, 2024). "CD163+ macrophages affect PD-L1 expression in tumor cells, and CD163+ M2 macrophages exert immunosuppressive effects by activating JAK/STAT signaling to produce IL-10 and promote PD-L1 expression in tumor cells." (PMID 38893259, 2024). "By isolating Tregs from liver tumors, we observed that the mRNA levels of several functional cytokines (IL‐10, IL‐35, TGF‐β1) in Tregs from Sox12△hep tumor were down‐regulated." (PMID 39072947, 2024).
tumor (continued). "Upon evaluation of the efficacy of the combination therapies, M-NP addition to the treatment program produced a strong elevation in the levels of IL-10 and TNF-α indicating activation of a powerful systemic anti-tumor immune response." (PMID 37612575, 2024). "Specific bacterial strains induce the production of interleukin-6 (IL-6), interleukin-10 (IL-10), and transforming growth factor-beta (TGF-β), promoting tumor growth and evading immune surveillance by inhibiting cytotoxic T cells and natural killer (NK) cells." (PMID 39044834, 2024). "In glioblastoma, Tregs inhibit the anti-tumor response and promote tumor-killing tolerance by secreting immunomodulatory cytokines (e.g., TGF-β and IL-10)." (PMID 39061427, 2024). "Pro-tumour cytokines such as vascular-endothelial growth factor α (VEGF-α) and the interleukins (IL) IL-4, IL-5, IL-6, IL-10, and IL-13 produced by T-helper (Th2) lymphocytes have also been linked to the pathogenesis of MCD." (PMID 40729293, 2024). "Concurrently, anti-inflammatory mediators like IL-10 and TGF-β play key roles in dampening effective anti-tumor immune responses." (PMID 39682256, 2024). "Meanwhile, IFN-γ or TNF-α from TAMs upregulate the PD-L1 expression of tumor cells, and IL-10 and TGF-β from TAMs influence the B7-H1 expression of tumor cells." (PMID 38672714, 2024). "SIRPα-Fc administration resulted in increased amounts of tumor-infiltrating macrophages, enhanced TNF-α production, and a reduction in IL-10 expression." (PMID 39335665, 2024). "Concurrently, regulatory T cells (Tregs) that release and maintain immunosuppressive cytokines like interleukin 10 (IL-10) and transforming growth factor-β (TGF-β) remain more prevalent in the tumour than in the surrounding healthy tissue." (PMID 38732225, 2024). "These cells release immunosuppressive cytokines, such as interleukin (IL)-10, IL-35, and transforming growth factor (TGF)-β, consequentially leading to the exhaustion and poor tumor infiltration of the immune effector cells and failure of tumor clearance." (PMID 39066359, 2024). "The selection of cytokines was based on their significant role in regulating the tumor microenvironment, including promoting either the Th1 (IL-2RA, IL-12(p40), IL-15, TNF-α, IL-1β, IL-1RA, and IFN-γ) or the Th2 (IL-4, IL-6, IL-8, and IL-10) profile." (PMID 39768997, 2024). "TAMs secrete a series of cytokines and inflammatory factors such as TGF-β), IL-6, IL-10, IL-13, IL-4 and TNF-α that promote tumour initiation, growth, metastasis, angiogenesis, proliferation and chemoresistance in HCC (Ref." (PMID 39320855, 2024). "Isatuximab can inhibit Treg proliferation and migration, suppress IL‐10 secretion, and enhance the cytotoxic capabilities of CD8+ T cells and NK cells against tumor cells." (PMID 39492834, 2024). "MDSCs exploit multiple mechanisms to hamper anti-tumor immunity such as the expression of transforming growth factor-beta, reactive oxygen species, prostaglandin E2 (PGE2), IL-10, arginase-1, and indoleamine dioxygenase." (PMID 38343540, 2024). "We first compared the contents of M2 macrophage markers, Arg-1, IL-10, CD163, CD206, and CRNDE in tumor tissues and para-cancerous tissues." (PMID 38822362, 2024). "They secrete IL-4, IL-10, and transforming growth factor-β (TGF-β), which facilitate tumor growth and metastasis." (PMID 39575419, 2024). "In contrast, in the presence of factors such as IL-4, IL-13, IL-10, or glucocorticoids, M2 macrophages produce IL-10 and TGF-β, acting in tissue remodeling, angiogenesis, and tumor progression." (PMID 38741166, 2024). "On the other hand, effector Tregs are also known for IL-10 secretion in TME of CRC patients, resulting in the inhibition of the Th17 cells, which are responsible for the inflammation and tumor immunity." (PMID 38658633, 2024). "Tumor-promoting and anti-inflammatory factors TGF β, IL10 and VEGF were significantly stimulated by rh SPP1 protein but inhibited by anti-SPP1 antibody." (PMID 38648200, 2024).
tumor (continued). "This suggests that aspirin can inhibit T cell function via the TIGIT-BCL2-BAX signaling pathway, reducing IL-10 and TGF-β1 secretion and improving effector T cell function, ultimately contributing to the inhibition of tumor progression." (PMID 39113892, 2024). "Consistent with their potential role in suppressing anti-tumour activities of T cells, CD163+ TAMs express a range of potent immunosuppressive molecules, including PD-L1, PD-L2, IL-10, and TGF-β." (PMID 38903497, 2024). "Contrarily, M2 macrophages, another common macrophage type, secrete a series of immunosuppressive factors, such as IL-10 and TGF-β, which inhibit the activity of CD8+ T cells and promote tumor growth." (PMID 38762523, 2024). "Dianzani C and others found that ICOS-Fc treatment inhibited tumor cell migration to the lungs in mice, increasing IL-17A and RAR-related orphan receptor C (RORc) expression while reducing IL-10 and Foxp3 expression." (PMID 39104717, 2024). "Tumor-infiltrating lymphocytes (TILs): In GBM, TILs often exhibit dysfunction and exhaustion caused by factors released by glioma and microenvironmental cells, including TGF-β, IL-10, and CCL2, which recruit Tregs, MDSCs, and TAMs to the tumor site." (PMID 38610954, 2024). "Despite this, there was evidence of anti‐tumor activity such as the low number of CD163+ cells, greater necrosis, high levels of IL‐10 and low levels of IL‐6 and IL‐27." (PMID 38600057, 2024). "DLBCL cells express both IL-10 and its receptor, eliciting an autocrine pathway of STAT3 activation that fuels tumor cell proliferation." (PMID 39281678, 2024). "M1 macrophages secrete γ interferon (IFN-γ) and other inflammatory cytokines, whereas M2 macrophages produce immunosuppressive cytokines, such as interleukin 10 (IL-10), which are involved in tumor immune escape in the TME and promote tumor cell proliferation." (PMID 38539232, 2024). "When comparing the tumour tissues to the healthy lung tissues, there was a notable increase in TGF‐β and IL‐10 concentrations as well as a decrease in IL‐15 levels, implicating an immunosuppressive microenvironment favouring tumourigenesis of LUAD." (PMID 38279870, 2024). "Conversely, IL-10, an anti-inflammatory cytokine produced by assorted cells including T cells, B cells, and monocytes, may manifest anti-inflammatory properties within the tumor microenvironment and suppress the activity of immune cells, diminishing their cytotoxic impact on the tumor." (PMID 39207449, 2024). "Tumor cells in the immunosuppressive TME secrete immunosuppressive factors such as TGF-β, prostaglandin E2 (PGE2), and IL-10 that downregulate the activation receptors of NK cells, thus preventing their activation." (PMID 39494330, 2024). "In the tumor microenvironment, TGF-β, IL-10, and IL-6 suppress NK cell activity and affect immunosuppressive cells and pro-inflammatory cytokines, decreasing the antitumor response of NK cells and promoting subsequent tumor evasion and progression." (PMID 39599846, 2024). "Morphine regulates immune factors (IL-2, IL-10, TGF-β, and PD-L1), thereby promoting tumor immune escape." (PMID 38361933, 2024). "The tumor-immune cells microenvironment augments PD-L1 expression with pro-inflammatory cytokines, such as IFN-γ, tumor necrosis factor α (TNF-α), IL-10, interleukin-1 (IL-1) and interleukin-6 (IL-6)." (PMID 38384472, 2024). "Furthermore, tumour associated macrophages and cancer associated fibroblasts secrete various proteins, including immunosuppressive cytokines, such as transforming growth factor-ß (TGF-ß), interleukin 10 (IL-10), indolamine-2,3-dixoygenase (IDO) and vascular endothelial growth factor (VEGF)." (PMID 39403376, 2024). "Neutralizing IL10 significantly increases the proportion of CD8 + T cells, leading to enhanced tumor cell death." (PMID 38844562, 2024).